CD4 (CD4 molecule)
Diseases named in the same sentence as CD4 in open-access papers (continued):
Sharing a sentence is not in itself a finding about the gene and the disease.
tumor (continued). "While this activation marker returned to baseline on Day 14 for CD8+ and non‐regulatory CD4+ T cells, dual expression of ICOS+/PD1+ Tregs was reduced 0.73‐fold (p = 0.0474), which also indicates a more immunostimulatory tumor microenvironment." (PMID 36176603, 2022). "Because of positive relation between CD4+TILs and tumor outcome, it can be inferred that regulatory subsets may be through downregulation of harmful inflammatory reaction and activated CD4+cells with anti-tumor activity and cytokine secretion could control tumor progression." (PMID 36319566, 2022). "The frequency of tumour-infiltrating CD4+TIGIT+ cells and CD8+PD-L2+cells positively correlated with a poor response to subsequent neoadjuvant treatment determined by tumour regression grade (p = 0.04 and p = 0.03)." (PMID 35366537, 2022). "Existing data in dual therapy (anti-CTLA-4 + anti-PD-1) also demonstrated the importance of CD4+ and CD8+ T-cell recruitment in the anti-tumor effect." (PMID 35433707, 2022). "iNKT cells promote the differentiation of MDSCs into functional DCs upon α-GalCer injection in a mouse model of colon carcinoma, leading to the activation of tumor-specific CD8+ and CD4+ T cells and the triggering of NK cell cytotoxicity." (PMID 35615083, 2022). "cDC1 is crucial in activating tumor-specific CD8+ T cells, whereas cDC2 promotes the activation of CD4+ T cells and has been known for driving anti-tumoral activities." (PMID 36497152, 2022). "Circulating CD4+ T cells can target cancer cell surface antigens and activate peripheral blood CD8+ T cells, allowing them to enter the tumor microenvironment and kill cancer cells." (PMID 36292195, 2022). "Animal studies have shown that the combination of tumor-specific CD8+ and CD4+ T cells enhances significantly antitumor response." (PMID 35008422, 2022). "The expression of PD-1 checkpoint receptor also significantly increased on CD8+ T cells in the liver and on both CD4+ and CD8+ T cells in the tumor suggesting recent activation of these cells." (PMID 35681695, 2022). "(B) Frequencies of CD4+ T cells, CD4+Foxp3+ Tregs, and CD8+ T cells within draining lymph nodes (dLN) and tumor of Asm-KO and Asm-WT mice were determined by flow cytometry." (PMID 36426850, 2022). "In tumor samples, TIL CD4/CD8 presented a CD39 increase and CD73 decrease, suggesting that CD39 expression can be an inhibitor of T cells." (PMID 36230810, 2022). "We found a statistically significant increase in production level of IFNγ in both CD4+ Th (p < 0.02) and CD8+ T-cells (p = 0.0079) in all tumor-bearing mice in comparison with control." (PMID 36555468, 2022). "Flow cytometry analysis of the TME revealed that the number of infiltrating immune cells, including CD3+, CD4+, and CD8+ T cells, as well as NK cells, was considerably reduced in B16F10-R tumours compared to that in B16F10-NR tumours." (PMID 36077671, 2022). "We assessed the expression of TIGIT in TILs using the MC38 tumor model, and the expression of TIGIT was significantly higher in TILs, including CD4+ TILs, CD8+ TILs, and NK cells, compared with the spleen." (PMID 35320940, 2022). "Increased frequency of CD4+ and CD8+ in Opn4KO tumors compared to Opn4WT was found, which is suggestive of increased migration of lymphocytes to the tumor site." (PMID 35562405, 2022). "Alternatively, the Co treatment, alone or with A, resulted in much lower frequency of CD4+ or CD8+ T cells with TNFα, and even more so IFNγ production in the tumor (CD4+ IFNγTNFα+: Co/A=17.2 ± 3.1, Ca/N=31.8 ± 4.1, p=0.0097)." (PMID 36419897, 2022). "TNFRSF4, CD4, and CD8 mainly expressed on the tumor stroma and displayed a co-localization pattern observed in both the separate and merged images." (PMID 35562682, 2022). "First, they enable phagocytic uptake of tumor cells by antigen-presenting cells, leading to subsequent antigen presentation to CD4+ and CD8+ T cells, stimulating the anti-tumor adaptive immune response." (PMID 36429020, 2022).
tumor (continued). "Type 1 immune responses are considered beneficial for effective anti-tumor immunity, and NK cells and T cells (CD8+ cytotoxic T lymphocytes and CD4+ Th1 cells) are considered prototypical producers of IFN-γ." (PMID 35300331, 2022). "Immunostimulatory cytokines produced by mature dendritic cells, in turn, recruit NK cells, CD4 T cells, and CD8 T cells, which can contribute to tumor regression and activate tumor-specific immunity." (PMID 36187936, 2022). "Based on the significant Flt3L-induced increase in cDC2s, that specialize in CD4+ T cell priming, and the striking effects of NDV on CD4+ Th1 effector cells, we sought to evaluate the role of CD4+ T cells for Flt3L+NDV-induced anti-tumor immunity in vivo." (PMID 36418317, 2022). "Dendritic cells, CD4 T cells, and CD8 T cells will undergo maturation or differentiation due to the continual presence of tumour neoantigens." (PMID 36531162, 2022). "Targeting the GITRL-GITR pathway activates CD4+ and CD8+ T cells, thereby promoting tumor suppression." (PMID 36160406, 2022). "Further analysis identified CD4 and CD8 co-expression by 10 out of 52 top expanded tumor-derived clonotypes with clonal frequency over 1%." (PMID 36185254, 2022). "CXCL9 is abundantly expressed in several solid tumors, including CM, and it stimulates the infiltration of CD4+T and CD8+T lymphocytes into tumor cell regions, hence boosting the response of cytotoxic T lymphocytes and destroying tumor cells." (PMID 35957907, 2022). "IHC analysis showed a significant increase of CD4 + T cells, CD8 + cytotoxic T cells and macrophage densities in the tumor treated with NBTXR3 + RT." (PMID 35659676, 2022). "Conversely, gene clusters A and C showed an immune-inflammation phenotype with high levels of leukocyte, CD4+ T cell, and CD8+ T cell infiltration, and exhibited high proliferation, suggesting high tumor growth in patients in these clusters." (PMID 35053610, 2022). "It is reported that almost a quarter of tumor-infiltrating lymphocytes (TILs) in the TME are in fact Tregs, while making up only about 5–10% of CD4+ T cells in the bloodstream." (PMID 36551992, 2022). "In addition, the ratio of CD4+/CD8+ T cells may be a critical parameter of anti-tumor immunity." (PMID 36476246, 2022). "We found that the tumor of the same patient had higher CCR5 expression than PBT, and the infiltration of CD4+ T cells and M2 macrophages were also higher." (PMID 35865011, 2022). "Dendritic cells that lack CD5 expression have also been shown to enhance CD4+ and CD8+ T cell activation and produce better anti-tumor responses." (PMID 35327505, 2022). "AN3025 significantly increased tumor infiltrating CD8+ T cells and CD4+ T cells, while anti-mouse PD-1 antibody showed less effects on tumor infiltrating CD8+ and CD4+ T cell in the same study." (PMID 35251028, 2022). "Interestingly, CD8+ T cells, CD4+ T cells, B cells, dendritic cells, and effectors of innate immunity, namely macrophages, polymorphonuclear leukocytes, and natural killer cells (NK), as well as all cell types within the tumor, are classified as tumor-infiltrating lymphocytes (TILs)." (PMID 35407463, 2022). "CD4+ T cells are influenced by the TME, leading to adopt pro-tumour functions and secret factors that support the tumour survival." (PMID 35406451, 2022). "CD4+ T cells are activated primarily by MHC class II antigen recognition and serve an important regulatory role in anti-tumor immune response." (PMID 35402261, 2022). "Consistently, cell profiling of BCG hydrogel-treated primary tumor showed increased frequencies of CD45+ immune cells, CD8+ and CD4+ T cells, NKT cells and NK cells, as well as iNOS+ M1 MΦ." (PMID 35732347, 2022). "We identified DEGs in both CD4+ and CD8+ T cells from tumor tissues relative to those from adjacent normal tissues." (PMID 36104333, 2022).
tumor (continued). "Some of the tumour infiltrating cells, e.g., CD4+, CD335+ cells, were increased in the tumours of all responding mice, whereas CD8+, CD141+ were increased and CD11b+ cells were decreased preferentially in R-115-treated mice." (PMID 36140243, 2022). "Tumor infiltrating dendritic cells (DCs), and TGF-β, IL-2, and indoleamine-2, 3-dioxygenase-1 (IDO-1) are all essential cells and molecules that promote CD4+ T-cell differentiation into Tregs." (PMID 35371055, 2022). "In this picture, it is found that CD4+ and CD8+ T cells taking up a large proportion in tumor-infiltrating immune cells in TME of HCC." (PMID 35092558, 2022). "In fact, when T cells are incubated with tumor cells in the presence of BiTEs, both CD8+ and CD4+ T cells become activated, followed by significant tumor cell lysis, with more pronounced MM cell killing by CD8+ over CD4+ T cells." (PMID 36330495, 2022). "We tested VISTA expression on CD4+ T cells and identified its role in TME with the NSCLC patients’ tumor tissues." (PMID 35122478, 2022). "Together, using a tumor-specific MHC class I-restricted TCR, our study depicted the functional and molecular characteristics of cytotoxic CD4+ TCR-Ts at the single-cell transcriptomic level, which revealed the multifaceted cytotoxic pathways for CD4+ TCR-Ts." (PMID 35928827, 2022). "The generated antibodies were functional as they blocked CD4 T-cell activation following their co-culture with OVA-pulsed MSC-IPr and mitigated E.G7 tumor growth in vivo." (PMID 35203247, 2022). "Targeting of in vivo DCs by modified L. monocytogenes induced the activation of CD4+ and CD8+ T cells and controlled mouse tumor growth." (PMID 35806328, 2022). "Anti-PD-L1 antibody administration suppressed tumor growth in the chimeras and resulted in the increased abundance of IFNγ+CD8+ and IFNγ+CD4+ T cells and decreased abundance of PD-1+CD8+ and PD-1+CD4+ T cells in dLNs." (PMID 35217706, 2022). "We analyzed immune cell infiltration analysis and found that CD8 T cells, memory resting CD4 T cells, and M2 macrophages were the most enriched components in the KIRC tumor immune microenvironment." (PMID 35371994, 2022). "On the other hand, high frequencies of CD4+TIM-3+, FoxP3+Helios+TIM-3+ Tregs and FoxP3−Helios+TIM-3+ T cells in circulation are associated with longer DFS in CRC patients, suggesting that T cells expressing TIM-3 could be activated cells with improved anti-tumor activities." (PMID 35655158, 2022). "Neoantigen vaccination was associated with a decrease in the percentage of regulatory T cells (Treg, CD4+CD25+FoxP3+) and, in particular, TIGIT+ Treg in the tumor, likely due to the increased absolute number of tumor-infiltrating CD4 T cells." (PMID 36569934, 2022). "We found that EVax treatment increased both CD4+ T and CD8+ T cell infiltration, while JHU038 increased CD8+ T cell numbers in tumor tissues." (PMID 35861366, 2022). "In here, we also found that in most tumor types, the RBM10 expression was positively correlated with the T cell CD4+ Th1 cell infiltration level and negatively correlated with the T cell CD4+ Th2 cell infiltration level." (PMID 39282149, 2022). "Since CD4+-TIL depletion accelerated the tumor growth, our results suggest that the balance between TIL-CD4+-Teff and immuno-suppressive environment inclusive of G-MDSC and M2 macrophage play critical roles in the mechanism of this tumor’s immunity." (PMID 35228603, 2022). "In contrast, a trend towards an increased ratio of CD4+ MAIT cells within tumors was observed, with CD4+ and DN MAIT cells constituting a significantly greater percentage of the tumor‐infiltrating MAIT cell population than in the circulation." (PMID 35028137, 2022). "Tregs, as a subtype of CD4+ T cells, accumulate in the TME and play vital roles in tumor metastasis." (PMID 36405735, 2022). "VCP was overexpressed in NSCLC tumor B cells, NSCLC PBLs, and tumor T cells, as well as a C4 /C9-CTLA CD4 T cell cluster." (PMID 35804895, 2022).
tumor (continued). "The secretion of TNF-α, IFN-γ, IL-6, and other cytokines by CD4+ T cells can change the TME, induce the local invasion of T lymphocytes into the tumor, inhibit the synthesis of DNA and RNA of tumor cells, and thus, induce the apoptosis of tumor cells." (PMID 36389763, 2022). "- Flow-cytometry and immunohistochemistry analysis of CT-26 KRAS G12C tumours after 4 days of sotorasib: increased infiltration of CD3+, CD4+ and CD8+ T-cells; increased infiltration of macrophages and CD103+ dendritic cells." (PMID 35251972, 2022). "In conclusion, these data enhanced our fundamental understanding of the importance of tumor-reactive CD4+ T cells in the context of ACT and expanded the spectrum of CD4+ T cell-mediated anti-tumor immunity." (PMID 35784297, 2022). "The systemic antitumour effect of the triple therapy disappeared only when CD4+, CD8+ T cells and NK cells were knocked out, and the distant tumour grew rapidly and even tended to surpass that in the control group." (PMID 34731284, 2022). "The first subtype is the immune-inflamed phenotype, which is characterized by the substantial presence of both CD4+ and CD8+ T cells in the tumor, often with myeloid cells and monocytes; the immune-related cells are in the vicinity of the tumor cells." (PMID 36421795, 2022). "Treatment of solid tumors with EZH2 inhibitors increases the recruitment and function of CD4+ and CD8+ effector T cells by induction of an inflammatory phenotype within tumor-infiltrating Tregs." (PMID 35795673, 2022). "Tregs are CD4 + T cells that promote tumor growth and are usually identified by the Foxp3 + CD25 + CD4 + T cell subset." (PMID 36207500, 2022). "According to this proposal, an IRIS phenomenon can be diagnosed by the enlargement of the tumor after initiating HAART, at least an 18-fold increase in CD4 count during this period, and shrinkage of the tumor without any radiation therapy or chemotherapy." (PMID 35141174, 2022). "Having established that succinate exposure impairs CD4+ and CD8+ T cell function, we then investigated the relevance of this in PC and PG by combining in vitro models of the tumor microenvironment with interrogation of patient samples." (PMID 35977513, 2022). "Neoantigen vaccines based on RNA, DCs or peptides aim to induce CD4+ and CD8+ T-cell responses and promote T-cell infiltration into the tumor core." (PMID 36477638, 2022). "Based on this, CD4+T cells are helper T cells, which can secrete cytokines and activate CD8+T cells to carry out anti-tumor effects and are the most important hub cells in adaptive immune response." (PMID 36118529, 2022). "Emerging cancer cells can be identified and killed by many immune cells in tumor treatment, such as CD8+ and CD4+ memory static T cells." (PMID 36686655, 2022). "In terms of tumor surveillance and elimination, APCs will provide them with cytotoxic T (CD8+) lymphocytes via HLA I Helper T (CD4+) cells which are also involved and are activated through the interaction of HLA II molecules with APCs." (PMID 35368886, 2022). "Consistently, CP treatment augmented the overall immune response, as evidenced by the elevated CD4+ and CD8+ T-cell levels in the tumor microenvironment (TME)." (PMID 36209170, 2022). "CD4+ or CD8+ TCR-Ts were transferred to mice through peritumoral injection on day 7 and day 14 after tumor implantation." (PMID 35928827, 2022). "FCM-NPs induced tumor-specific cell-killing CD8+ IFN-γ+ T cells, and reduced the number of CD4+ CD25+ Foxp3+ Treg cells simultaneously, promoting the anti-tumor immune response." (PMID 35251013, 2022). "Recently activated CD4+, pre-exhausted CD8+, and proliferative CD8+ T cells significantly increased in tumor regions, while most transitional memory CD4+ T cells were in normal tissue." (PMID 35440049, 2022). "Treatment with HHIs leads to upregulation of MHC-I on BCC cells and increased infiltration of CD4+ and CD8+ T cells into the tumor." (PMID 36230474, 2022).
tumor (continued). "The classical lymphocyte subsets include CD3+, CD4+, CD8+, B, and natural killer (NK) cells, which are essential for regulating the immunity and specific killing of tumor cells." (PMID 36051923, 2022). "To investigate the role of CD4+ and CD8+ T-cell subsets in anti-tumor activity, we evaluated the specific lysis capacity of the CAR-T cells via co-cultivation with GFP + CD20+ Raji cells in an effector to target ratio (E:T) of 1:1." (PMID 36298713, 2022). "The CD4+ and CD8+ cells, were distributed in the region of TILs and less frequently around the tumor." (PMID 35195152, 2022). "However, baseline CD4+ T cells present in KrasG12D lungs may have a tumor-promoting function." (PMID 35565302, 2022). "The tumor antigens can be mediated by both class I and class II MHC channels through internalized transgene expression that triggers CD4+ and CD8+ T-cells." (PMID 36560420, 2022). "Drebrin1-expressing cells were most prominently represented in the exhausted tumor-infiltrating CD8+ T cell clusters at the single-cell level, although CXCL13 was expressed in the exhausted tumor-infiltrating CD4+ and CD8+ T cell clusters." (PMID 36430217, 2022). "We next performed IHC immunostaining for several established markers of distinct immune subclasses in human MPNST tumor tissue, including CD45 (pan-leukocyte), CD3 (T cells, CD4+ and CD8+ subsets), CD68 (macrophages/monocytes), and CD20 (B cells)." (PMID 35852856, 2022). "Characterized as CD4+CD25+FoxP3+ T cells, Tregs are responsible for carrying out immunosuppressive activities in the TME to drive tumor progression." (PMID 35345849, 2022). "Moreover, Tim-3 could mediate CD4+ cell depletion which promoted the growth of tumor cells." (PMID 36368952, 2022). "In MM mouse model with high tumor infiltration (MM %> 40%), we consistently found that the proportion of CD8+ T cells significantly decreased in their BM, whereas CD4+ T cells remained stable." (PMID 36532059, 2022). "But the statistical results showed that CISD2 expression was significantly correlated with several types of tumor-infiltrating immune cells in LGG, including B cells, CD8+ T cells, neutrophils, and CD4+ T cells in TIMER." (PMID 35493303, 2022). "Previous studies have shown that Salmonella enterica serovar Choleraesuis (Salmonella choleraesuis) can significantly inhibit tumor growth, but in CD4+ or CD8+ T lymphocyte depleted mouse models, the inhibition of tumor growth is significantly reduced." (PMID 35522104, 2022). "The results showed that in 32 tumor types, DOK5 expression was crucially related to CD4+ T cells, CD8+ T cells, neutrophils, macrophages, and dendritic cells." (PMID 35036444, 2022). "Mechanistically, celecoxib inhibited the COX2 effect and suppressed PGE2 production, which in turn elevated the infiltration of CD3+, CD4+, and CD8+ T cells, as well as NK cells, resulting in the suppression of tumour growth." (PMID 36077671, 2022). "PTT-induced dead tumor cells release tumor-derived antigens that stimulate the host immune system, and the percentages of all cells infiltrating CD3+ T cells, CD4+ T cells, and CD8+ T cells in the tumor dramatically increased." (PMID 35651605, 2022). "Anti-tumor immune cells mainly contain CD8 + cytotoxic T cells, effector CD4 + T cells, natural killer cells, DCs, M1 macrophages, and N1 neutrophils." (PMID 35372408, 2022). "Conversely, the deletion of CD4+ T cells contributed to the recruitment and accumulation of CD8+ T cells as well as elevated levels of IFN-γ, with a markedly tumor vascular normalization phenotype." (PMID 36439137, 2022). "In the context of combination radiation and immunotherapy, a major finding is that ENI increases local and distant failure by decreasing the systemic CD4 and CD8 effector T cells responsible for tumor control." (PMID 36385142, 2022). "Other in vivo studies reported the increase of tumor MHCI and paclitaxel-dependent CD8+/CD4+ T cells infiltrated in a murine ovarian cancer model." (PMID 36003395, 2022).